ANXA1 (annexin A1)
Diseases named in the same sentence as ANXA1 in open-access papers (continued):
Sharing a sentence is not in itself a finding about the gene and the disease.
tumor (continued). "Up-regulation of miR-196a2 and down-regulation of annexin A1 were associated with poor differentiation, larger tumor size, and advanced clinical stage." (PMID 29091952, 2017). "Evaluating the tumor subtypes, ANXA1 high expression was specifically associated with an increased mortality in HER2 positive patients (10-years OS: HRadj = 1.60; 95 % CI = 1.06–2.41 and 10-years BCSS: HRadj = 1.70; 95 % CI = 1.17–2.45)." (PMID 26137966, 2015). "In patients with gastric cancer, evidence shows that the loss of ANXA1 is associated with tumor progression, lymph node metastases, and poor prognosis." (PMID 24782913, 2014). "Knocking out ANXA1 in perivascular invading cells induced notable phenotypic shifts, including the loss of tumor bulk and perivascular involvement, while acquiring an AC-like cell state and diffuse invasion, ultimately leading to increased median survival in mice." (PMID 40683881, 2025). "In addition, NRF2 transcriptional upregulation of ANXA1 expression promotes tumor‐associated macrophage recruitment and M2 polarization." (PMID 40583858, 2025). "In summary, these results indicate that ANXA1 can regulate the expression of GOT1, promote the adaptive ability of glutamine metabolism mediated tumor associated oxidative stress, further promote tumor growth, and inhibit ANXA1 combined with glutamine deficiency to inhibit tumor growth." (PMID 40390008, 2025). "Moreover, several studies support that ANXA1 is frequently linked to advanced stage, aggressive tumor behavior, and poor outcome, being consequently regarded as an independent prognostic marker of a patient’s survival." (PMID 41283264, 2025). "ANXA1 also plays a significant role in the progression of other types of cancer, including gastric cancer, with its overexpression being associated with peritoneal metastasis and advanced tumor stages." (PMID 41283264, 2025). "The elevated expression of ANXA1 in TNBC may be linked to its multifaceted regulatory roles within the tumor microenvironment." (PMID 40744683, 2025). "Additionally, understanding ANXA1 biology is complex as it is susceptible to proteolytic cleavage in several physiological contexts including within tumour tissue and can be present in the nucleus, cytoplasm or extracellular environment." (PMID 38200229, 2024). "Furthermore, since a syngeneic model has a fully functioning immune system, both direct and immune-mediated anti-tumour activity caused by ANXA1-targeted therapy can be observed." (PMID 38200229, 2024). "AnxA1 is well-implicated in the modulation of tumor inflammation via NF-κB activation." (PMID 35897832, 2022). "In particular, ANXA1 was associated with worst outcomes in cancer patients by enhancing regulatory T‐cell functions, promoting mast cell infiltration and promoting polarization and activation of tumour‐associated macrophages." (PMID 35146757, 2022). "As an anti‐inflammatory protein, ANXA1 has always been associated with tumour immunity." (PMID 35770335, 2022). "Thus, the complex ANXA1/EVs is involved in modulating the interaction between TAMs and CAFs, that regulate tumor-associated inflammation and between TAMs and endothelial cells that improve the angiogenesis." (PMID 34681678, 2021). "Notably, the CCIs involved epithelial tumor cells, cancer-associated fibroblasts, and tumor-associated macrophages through integrin-related and ANXA1–FPR pairs." (PMID 34522794, 2021). "Finally, loss of Annexin A1 resulted in the loss of a discrete CD24+/Sca1− population containing putative tumor initiating cells." (PMID 33800279, 2021). "In particular, loss of ANXA1 retarded tumor burden and suppressed lung metastasis in vivo." (PMID 33531975, 2021). "ANXA1 is the first member of the family of membrane-linked proteins that inhibits the transcription of nuclear factor kappa B (NF-κB) by blocking its binding to DNA, thereby inhibiting the proliferation of tumour cells and promoting their apoptosis." (PMID 31949471, 2019).
tumor (continued). "Besides the large spectrum of physiological functions, rising evidences implicated ANXA1 in the process of carcinogenesis in a tumour-specific manner." (PMID 30518142, 2018). "Furthermore, ANXA1 deficient mice exhibit reduced tumour growth and enhanced survival in vivo, possibly due to increased M1 macrophages within the tumor microenvironment." (PMID 29263330, 2017). "Annexin A1 has been previously linked with various cancers as a tumor suppressor protein." (PMID 23786757, 2013). "In pathology, AnxA1 has been implicated directly or indirectly in tumor cell growth." (PMID 22011168, 2011). "ANXA1 has also been observed to influence immune cells and the tumour microenvironment by enhancing regulatory T-cell function, enhancing the polarisation and activation of M2 tumour-associated macrophages, suppressing dendritic cell activation and impairing CD8+ T-cell anti-tumour immunity." (PMID 38200229, 2024). "Additionally, CTHRC1 overexpression induced tumor associated macrophage infiltration via AnxA1/FPR1 and GRN/TNFRSF1A signaling pathway, indicating CTHRC1 might be a promising predictive factor for immunotherapy." (PMID 37404760, 2023). "Since ANXA1 was recently found to be downregulated in multiple human cancers in vivo, the fact that the ANXA1 N-terminal associates with cancer biomarkers cytokeratins 8 and 18 could provide some insights into tumor suppression by other annexins, including ANXA7." (PMID 37240163, 2023). "The results of univariate analysis based on sex, age and tumor status suggested that ANXA1 was significantly associated with the survival and status of ES patients (P<0.001) and that the low HR value (HR<1) of ANXA1 indicated that it may be a low risk factor for prognosis in ES patients." (PMID 36988561, 2023). "Importantly, ANXA1 deficient mice exhibit reduced tumor growth and enhanced survival." (PMID 35664067, 2022). "Therefore, we tried to determine whether ANXA1 is associated with the tumour‐immune system in patients with GBM." (PMID 35770335, 2022). "Furthermore, besides characterization of anxA1 expression using IHC, we would also like to identify antibody capable of binding cell membrane–associated anxA127-346 for tumor uptake imaging study in tumor vasculature anxA1 positive rodent model." (PMID 32497150, 2020). "Thus, it was of interest whether ANXA1 expression associates with tumor heterogeneity, which was assessed by mutation load and a mutant allele tumor heterogeneity (MATH) algorithm, and with cytolytic activity score (CYT)." (PMID 31461932, 2019). "However, future studies on PC patients will be needed to determine whether ANXA1 could represent a potential diagnostic, prognostic or predictive biomarker by correlating the progression and/or metastatic rate of the tumour to the protein expression." (PMID 25510623, 2014). "Proteomic profiling of MSC-exosomes identified key proteins, including ANXA1, ANXA2, EEF2, LGALS1, and PKM2, associated with tumor regeneration and chemotherapy response." (PMID 41683993, 2026). "Conversely, genes linked to DNA-damage responses and apoptotic pathways (H2AX, DAXX, ANXA1) demonstrated relatively higher expression in prehabilitation-treated tumor regions." (PMID 41596590, 2026). "Depending on the tissue and cancer type, ANXA1 has been found upregulated or downregulated, and it is described as a tumor promoter or a tumor suppressor." (PMID 40361334, 2025). "With this in mind, the Proteogenomics Research Institute for Systems Medicine (PRISM) investigated the proteomic map of tumor endothelium and discovered a potential target, Annexin A1 (37 kDa), which is overexpressed on tumor endothelial caveolae." (PMID 40143074, 2025). "CD68, however, was co-expressed with ANXA1 throughout on the majority of TAMs, both in the stroma and in tumor nests." (PMID 40361334, 2025).
tumor (continued). "ANXA1’s high expression in pre-therapeutic biopsies has been strongly correlated with limited tumor regression following nCRT and with poor survival in LARC patients." (PMID 41283264, 2025). "Remarkably, Anxa1 restoration resulted in significantly smaller tumors, markedly increased tumor-free survival, and extended latency compared with the control group." (PMID 39896470, 2025). "This 5-AZA-mediated loop allowed us to suggest that the induction of ANXA1 expression/action from the other cell components of the microenvironment can revert the tumor cell phenotype." (PMID 40227604, 2025). "To further investigate the role of ANXA1 in tumor growth in vivo, we constructed a subcutaneous xenograft tumor model." (PMID 40390008, 2025). "Consistent with the results of the tumor curve, quantitative analysis of whole slide imaging revealed that ANXA1 overexpression led to a decrease in the density of both CD8+ T cells and CD11c+ DCs." (PMID 40484878, 2025). "Studies suggest that ANXA1 can induce the generation of M2-like macrophages and microglia through its receptor, thereby promoting a Treg-driven immunosuppressive tumor microenvironment." (PMID 41267080, 2025). "Previous studies support that ANXA1 plays a major role in therapy resistance, showing a significant potential as a therapeutic target in different neoplasias." (PMID 41283264, 2025). "Taken together, the current data show that ANXA1 plays a major role in several oncogenic processes, such as angiogenesis, DNA damage response, tumor cell proliferation, along with cancer cell invasion and migration." (PMID 41283264, 2025). "We found that multiple cells with an amoeboid and ramified morphology co-expressed CD45 and ANXA1 in the tumor stroma, showing the protein’s presence on immune cells." (PMID 40361334, 2025). "Spatial distribution analysis using the STOmics DB database also showed that SUSD3 co-localized with the tumor cell marker ANXA1 and the T cell marker CCR7 in SKCM cancer tissues, indicating spatially similar distributions." (PMID 40191190, 2025). "Consistently, the orthotopic mouse PDAC model also confirmed that ANXA1 knockdown significantly inhibited tumor growth, while ANXA1 overexpression promoted tumor progression." (PMID 40484878, 2025). "The results demonstrated that knockdown of ANXA1 exhibited potent anti-tumor efficacy, which was further enhanced by anti-PD-1 blockade antibody." (PMID 40484878, 2025). "ANXA1 facilitates dendritic cell (DC) interactions with tumor debris by binding to formyl peptide receptor 1 (FPR1), while HMGB1 drives DC maturation by interacting with TLR4." (PMID 40004078, 2025). "Previous studies showed the possibility of annexin A1’s (ANXA1) involvement in the immunosuppressive tumor microenvironment in SCLC, and there are studies showing the direct effects of ANXA1 modulation on cancer cell aggressiveness." (PMID 40361334, 2025). "The mechanism study shows that tumor cell directly triggers apoptosis of DCs through molecular pair ANXA1:FPR1/3." (PMID 40484878, 2025). "RNA levels and protein activity of CD44, TNF Receptor Superfamily Member 1A (TNFRSF1A), and ANXA1 were elevated in these high NRF2 tumor cells." (PMID 40583858, 2025). "In this scenario, the immune system is known to play a crucial role in the regulation of tumor survival and is one of the most described system in which ANXA1 carries out its typical actions." (PMID 40227604, 2025). "Tumor growth was significantly inhibited in mice injected with ANXA1-knockdown HUCCT1 and HCCC9810 cells compared to the control group (**p < 0.01)." (PMID 40390008, 2025). "ANXA1-KO cells had a higher tendency to grow as a low-density tumor, and their morphology shifted from cell aggregates to more diffusely growing elongated tumor cells." (PMID 40683881, 2025). "ANXA1 plays a pivotal role in tumor progression and in different cellular processes, e.g., cell proliferation, differentiation, migration, and apoptosis." (PMID 41283264, 2025).
tumor (continued). "To assess differentially expressed genes (DEGs) in the ANXA1-high and -low tumor subsets, we performed DEG analysis for two focused gene sets of oncological and onco-immunological importance." (PMID 40361334, 2025). "Conversely, tumor growth was significantly accelerated in mice injected with ANXA1-overexpressing RBE cells (***p < 0.001)." (PMID 40390008, 2025). "Cells from the diffusively invading ANXA1-KO tumors exhibited a transition from the MES- and OPC-like states observed in control ANXA1-WT tumor cells, favoring NPC- and AC-like states." (PMID 40683881, 2025). "Exosomal proteins including HSP90 and ANXA1 facilitate extracellular matrix remodeling and immune evasion, thereby influencing tumor growth and metastasis." (PMID 41154440, 2025). "Altogether, our results showed that the upregulation of ANXA1 by NRF2 promotes the recruitment and M2 polarization of tumor‐associated macrophages." (PMID 40583858, 2025). "Further validation across multiple datasets, including TCGA-CHOL, demonstrated elevated ANXA1 expression in tumor tissues compared to controls, with statistically significant differential expression." (PMID 40390008, 2025). "It was proved that sh-PRSS22 suppressed the PRSS22 and PD-1 protein expressions and induced ANXA1 protein expression in GC tumor tissues." (PMID 41497316, 2025). "Another important ANXA1 characteristic is its ability to regulate the epithelial–mesenchymal transition (EMT)—a process that can either stimulate or inhibit tumor invasion." (PMID 41283264, 2025). "The results consistently demonstrated significantly higher ANXA1 expression in tumor tissues than in normal tissues." (PMID 40390008, 2025). "Our research has focused on ANXA1, a protein that has a dual role in cancer, acting both as an oncosuppressor and as an oncogene, depending on the cellular context and the type of tumor." (PMID 40227604, 2025). "RT-qPCR analysis revealed that ANXA1 expression in tumor tissues was significantly higher compared to normal tissues." (PMID 40390008, 2025). "In detail, our results showed that the 5-AZA-mediated ANXA1 overexpression affects only poorly differentiated and more aggressive cells, indicating its role in tumor prognosis and in the definition of a targeted therapeutic plan." (PMID 40227604, 2025). "ANXA1 was found to be significantly upregulated in tumor tissues and cells, and both in vitro and in vivo experiments confirmed its close association with ICC development." (PMID 40390008, 2025). "Further investigation revealed that the annexin A1 in the tumor endothelium exists as a truncated (34 kDa) form which is potentially induced by the tumor environment." (PMID 40143074, 2025). "Beyond serving as markers, proteins such as ANXA1 and HSP90 are known to actively modulate tumor–immune interactions; ANXA1 can influence macrophage polarization, while HSP90 acts as a chaperone for oncogenic signaling molecules." (PMID 41154440, 2025). "ANXA1 exhibits multiple roles in cell physiology and is recognized as a multifunctional protein that is involved in tumorigenesis and resistance to tumor therapy." (PMID 41283264, 2025). "To investigate the role of exogenous ANXA1 derived from the tumor microenvironment, we treated CAL27 with Ac2-26, an ANXA1 mimetic peptide." (PMID 40227604, 2025). "Emerging evidence from tumor microenvironments further demonstrates that ANXA1 modulates the maturation of dendritic cells and macrophages, leading to reduced T cell activation and immune evasion." (PMID 40977888, 2025). "On the contrary, our study unravels a direct cellular interaction between tumor cells and DCs (ANXA1:FPR1/3), which induces apoptosis of DC." (PMID 40484878, 2025). "To assess ANXA1’s role in tumor biology, we focused on two established hallmarks of cancer: the Warburg effect, which involves metabolic reprogramming, and the epithelial–mesenchymal transition (EMT)." (PMID 40361334, 2025).
tumor (continued). "An antibody targeting the truncated Annexin A1 protein was shown to rapidly pump across the tumor endothelium, reaching >100 fold more than other antibodies and exceeding peak blood fluorescence signal within one hour." (PMID 39982229, 2025). "We found no ANXA1 co-expression with CD3 or CD19 in any of the tumors, indicating that ANXA1 is expressed on tumor cells and TAMs in the TME." (PMID 40361334, 2025). "In the tumor microenvironment, the exogenous form of ANXA1 has been shown to stimulate the cellular components." (PMID 40227604, 2025). "Added to its well-established roles in cytokine regulation and inflammation, ANXA1 significantly contributes to tumor angiogenesis." (PMID 41283264, 2025). "ANXA1 regulates macrophage polarization by binding to formyl peptide receptors (FPRs), promoting the formation of M2 macrophages, which suppress anti-tumor immune responses." (PMID 40390008, 2025). "Collectively, these results establish ANXA1 as a critical regulator of the senescence program and highlight its tumor-suppressive role in oral squamous neoplastic progression." (PMID 39896470, 2025). "This study highlights the effectiveness of an antibody targeting annexin-A1 (ANXA1) in inhibiting cancer cell proliferation and tumor growth by arresting the cell cycle in the G1 phase." (PMID 39458945, 2024). "The band pattern of Annexin A1 showed hardly any differences between the tumor and the control tissue." (PMID 38893148, 2024). "It was also suggested that ANXA1 can operate as tumor suppressor gene because it can modulate proliferative function of estrogens." (PMID 38892394, 2024). "Spatiotemporal ANXA1 expression patterns in heterogeneous tumor ecosystems facilitate immunosuppression of the microenvironment." (PMID 38645221, 2024). "Our results showed increased levels of IGFBP7 and ANXA1 in LSCC compared to controls for all tumor stages." (PMID 38893148, 2024). "High ANXA1 expression correlates with hyperproliferation of AML cells because ANXA1 interacts with NICD to target this tumor suppressor for degradation." (PMID 39447086, 2024). "ELISAs on exosomes, on the other hand, did show significant overexpression of ANXA1 in tumor samples compared to controls except T2 (T1: FC = 2.5, p < 0.01; T2: FC = 1.9, p = n.s.; T4: FC = 3.0, p < 0.01; T1–T4: FC = 2.5, p < 0.01)." (PMID 38893148, 2024). "Annexin A1 was significantly downregulated in the serum of all tumor stages compared to controls, except T4 (T1: FC = 0.6, p < 0.05; T2: FC = 0.6, p < 0.01; T3: FC = 0.6, p < 0.01; T4: FC = 1.0, p = ns)." (PMID 38893148, 2024). "The dynamic expression levels of ANXA1 were confirmed by ST data analysis, demonstrating a substantial increase in the bulk levels of ANXA1 RNA (located in both healthy epithelium and tumor spots) along malignant transition routes." (PMID 38645221, 2024). "In gynecological cancers, ANXA1 promotes tumor progression by inhibiting apoptosis and facilitating autophagy, thus providing cancer cells with mechanisms to survive under adverse conditions." (PMID 38892394, 2024). "Compared to CPVLlow TAMs, CPVLhi TAMs received more GAS6 signals from fibroblasts, endothelial cells and dendritic cells, also, more ANXA1 signals from neutrophils, monocytes, dendritic cells, fibroblasts, endothelial cells, and tumor cells." (PMID 39776914, 2024). "The binding specificity along with the anti-cancer activity demonstrated in this study suggests MDX-124 is a strong therapeutic antibody candidate for patients with tumours expressing high levels of ANXA1." (PMID 38200229, 2024).